IL17A (interleukin 17A)
Diseases named in the same sentence as IL17A in open-access papers (continued):
Sharing a sentence is not in itself a finding about the gene and the disease.
psoriasis (continued). "It was therefore unexpected that therapeutic targeting of IL-17A (Secukinumab) or the IL-17 receptor (brodalumab) in phase II studies was less successful in RA than in other inflammatory conditions such as psoriasis." (PMID 30915067, 2019). "The autoimmune skin disease psoriasis—which is the most prevalent IL-17A-dependent disease—is also correlated with an increased cardiovascular burden." (PMID 31396305, 2019). "miR-340 was decreased in T cells from the Imiquimod psoriasis mouse model, thus increasing the release of IL-17A." (PMID 30761124, 2019). "In contrast, inhibition of PI3Kδ suppresses IL-17A expression through the regulation of NF-kB activity in a murine model of asthma and in imiquimod-induced psoriasis-like dermatitis." (PMID 31736982, 2019). "So far, the clinically relevant signaling in psoriasis is mediated mostly by IL-17A and IL-17F; both act through the same receptor, but have different potencies." (PMID 30909615, 2019). "Combined deletion of EP2 and EP4 selectively in T cells suppressed accumulation of IL-17A+ and IL-17A+IFN-γ+ pathogenic Th17 cells and abolished skin inflammation in an IL-23–induced psoriasis mouse model." (PMID 29935220, 2019). "In human psoriasis, IL-17A blockade in established disease displays a striking therapeutic efficacy, indicating the critical contribution of IL-17A to the pathogenesis of psoriasis." (PMID 31316164, 2019). "Secukinumab is a monoclonal antibody and a first-in-class anti-IL-17A agent developed to target and block the action of IL-17A, an active protein in the inflammatory response that occurs in psoriasis." (PMID 31214257, 2019). "An aberrant production of IL-17A disrupts the appropriate immune responses and promotes the development of various inflammatory diseases, including psoriasis, rheumatoid arthritis, Crohn’s disease, etc.." (PMID 30744173, 2019). "ERK phosphorylation can also activate Th17 cells and then promote the secretion of inflammatory cytokines TNF-α, IL-6, and IL-17A, which positively correlate with psoriasis." (PMID 31824416, 2019). "The IL-23-IL-17A axis plays a critical role in the pathogenesis of psoriasis, which is demonstrated by the substantial success of biological agents targeting IL-23 and IL-17A in the treatment of psoriasis." (PMID 31440249, 2019). "Dual-secreting Th17 T cells presumably are the predominant sources of the psoriasis phenotype-driving cytokines, IL-17A and IL-22." (PMID 31019502, 2019). "The proinflammatory cytokine IL-17A plays critical roles in the pathogenesis of autoimmune diseases, such as psoriasis, rheumatoid arthritis (RA), psoriatic arthritis, and ankylosing spondylitis." (PMID 31318609, 2019). "The IMQ-induced psoriasis-like skin condition in mice is mediated by several crucial cytokines, of which IL-17A and IL-22 are known to activate PI3K/Akt signaling in epidermal keratinocytes to induce abnormal cell proliferation." (PMID 31252620, 2019). "We have recently shown that vascular dysfunction in murine psoriasis is correlated with peripheral IL-17A levels and neutrophil infiltration into the aortic vessel wall and with the severity of skin disease." (PMID 31396305, 2019). "Currently, two IL-17A antagonists are available for the treatment of psoriasis: ixekizumab (approved in 2016) and secukinumab (approved in 2015)." (PMID 31673756, 2019). "The effects of IL-17A are situational; in murine colitis models, IL-17A functions in a tissue-protective manner, while the pro-inflammatory role of IL-17A has been delineated in arthritis and psoriasis in other contexts." (PMID 31164624, 2019). "This led to the assumption that upregulation of IL-17A in psoriasis inhibits WNT signaling in osteoblasts and osteocytes, thereby reducing bone formation rate." (PMID 31089877, 2019). "On the molecular level, chronic IL-17A/IL-23 signaling was found to drive the development of the most common subtype of psoriasis, psoriasis vulgaris." (PMID 31622280, 2019).
psoriasis (continued). "An increased expression of IL-17A and accumulation of Th17 cells were also found in the lesional skin of psoriasis patients." (PMID 31440249, 2019). "A further consideration is the success in therapeutic targeting of inflammatory Th17 cells in conditions such a psoriasis, or multiple sclerosis via antibodies against interleukin-17A (IL-17A) or IL-12p40." (PMID 31229354, 2019). "To address these questions, we generated keratinocyte-specific IκBζ-deficient mice (K14-Cre Nfkbiz KO) and investigated IMQ-, IL-36–, and IL-17A–mediated psoriasis induction in these mice." (PMID 31622280, 2019). "Ixekizumab is a humanized monoclonal antibody with a selective inhibition of IL-17A and approved for the treatment of moderate to severe psoriasis." (PMID 32010143, 2019). "The role of IL-17A in the inflammatory pathogenesis for psoriasis has thus been given credence through the clinical effect of its inhibition." (PMID 31488067, 2019). "Members of the IL-17 family that are now recognized as critical cytokines altering skin function in psoriasis and psoriatic arthritis are IL-17A, IL-17C, and IL-17F." (PMID 31827374, 2019). "Over the last decade, targeted therapies have substantially improved our capacity to reduce signs and symptoms of psoriasis patients to an extent that—with the advent of biologics blocking IL-17A—“clear skin” became a feasible treatment goal." (PMID 32010143, 2019). "Examples include etanercept (Enbrel®), a TNF-α antagonist and secukinumab, an antibody anti-IL-17A antagonist for psoriasis treatment." (PMID 31540162, 2019). "The excellent therapeutic efficacy of anti-TNF-α/IL-23/IL-17A biologics for psoriasis point to the central role of the TNF-α/IL-23/IL-17A axis in its pathogenesis Additionally, genetic and environmental factors are known to be involved in its pathogenesis." (PMID 31683543, 2019). "Psoriasis is considered a T cell-mediated disease, because T cell-derived cytokines such as IL17A and IL22 are responsible for the hyperproliferation and aberrant differentiation of keratinocytes that ultimately leads to psoriatic plaque formation." (PMID 31815151, 2019). "Psoriasis is a prototypic IL-17A and Th17 cell mediated autoimmune disease where targeting the inhibition of IL-23/IL-17 axis is a clinically validated approach for treatment." (PMID 31776355, 2019). "As of today, interfering with IL-17A or IL-23 are the most efficient treatment modalities against psoriasis." (PMID 31402919, 2019). "Mice with CARD14 genetic mutations (CARD14E138A/+ and CARD14DQ136/+) were shown to spontaneously develop psoriasis-like disease due to hyper-activation of NF-κB and enhanced activation of IL-17A signaling in keratinocytes." (PMID 31130981, 2019). "This retrospective review evaluated 100 consecutive patients with psoriasis receiving anti-IL-17A therapies who were checked with at least twice QFT-GIT between 2016 and 2019 in National Taiwan University Hospital, Taipei and Hsin-Chu, Taiwan." (PMID 31881026, 2019). "Based on these considerations, highly specific and molecular therapies targeted against single cytokines or their receptors such as the IL-17A system appear to be promising regarding cardiometabolic comorbidities in psoriasis." (PMID 32010143, 2019). "Our IL-17A-driven mouse model of severe psoriasis combines the psoriasis-like skin inflammation with cardiovascular disease as seen in patients with severe psoriasis." (PMID 31480330, 2019). "Although T cells produced more IL-17A in both psoriasis and EAU model, they were defective in migration to the skin but not to the inflamed eye." (PMID 31616442, 2019). "IL-17A is considered the key cytokine in the inflammatory process of psoriasis because it has a direct influence on the activation and hyperproliferation of keratinocytes." (PMID 31101850, 2019). "In the imiquimod-induced psoriasis mouse model, the intradermal administration of ADMSCs inhibits IL-17A and TNF-a, and suppresses the IMQ-induced inflammation." (PMID 31824416, 2019).
psoriasis (continued). "An excellent therapeutic response to biologics indicates a pivotal pathogenic role of interleukin (IL)-4/IL-13 signaling in AD and the tumor necrosis factor (TNF)-α/IL-23/IL-17A axis in psoriasis." (PMID 31683543, 2019). "Canonical pathway analysis of non-lesional differences compared to healthy skin resulted in the identification of ‘Role of IL-17A in Psoriasis’." (PMID 31388062, 2019). "Correlation (R-values) of IL17A, IL22 and IL23A in psoriasis with genes linked to atopic dermatitis susceptibility through genome-wide association studies." (PMID 31019502, 2019). "We also used this strategy to correlate the expression of IL17A, IL22, and IL23A with genes linked to psoriasis susceptibility identified through genome-wide association studies (GWAS)." (PMID 31019502, 2019). "Because clinical TB symptoms and signs are often preceded by QFT-GIF seroconversion, this result further supports the safety of anti-IL-17A agents in patients with psoriasis for LTBI." (PMID 31881026, 2019). "Because topical application of IMQ triggers TLR-mediated inflammation that activates dermal γδ T cells to produce IL-17A2, which plays a critical role in the pathogenesis of psoriasis, we next examined serum IL-17A levels in mice." (PMID 31659208, 2019). "Pathways affected by the genes with elevated expression include Calcium signaling, Agranulocyte Adhesion and Diapedesis, Actin Cytoskeleton Signaling, TR/RXR Activation and Role of IL-17A in Psoriasis." (PMID 31089182, 2019). "While IL-17A knockout mice develop significantly less severe psoriasis and EAU, treatment with anti-IL-17A antibody markedly reduced inflammation in both psoriatic and EAU mice." (PMID 31616442, 2019). "IL-23 drives the expansion of Th17 T cells that produce IL-17A/F, which is another set of cytokines whose role is pivotal in the pathogenesis of psoriasis." (PMID 30909615, 2019). "Diseases such as colitis, inflammatory bowel disease (IBD), dermatitis, psoriasis, asthma, and chronic obstructive pulmonary disease (COPD) caused by chronic inflammation are rooted by dysregulated IL-17A signaling." (PMID 31736982, 2019). "In a mouse model of psoriasis, the expression of miR-340 was decreased, and treatment with miR-340 suppressed the expression of endogenous IL-17A and alleviated the clinical severity of psoriasis." (PMID 30634634, 2019). "T cells, especially the IL-17A-producing Th17 cells, have been shown to play a dominant role during the pathogenesis of multiple autoimmune diseases including psoriasis and EAU." (PMID 31616442, 2019). "First antibodies that target IL-17A or its receptor IL-17RA are approved for the treatment of psoriasis." (PMID 32010143, 2019). "The main source of IL-17A in psoriasis patients is Th17 cells, and these significantly accumulate in the lesional skin and clinically resolved psoriatic lesions of psoriasis patients." (PMID 31440249, 2019). "The IL-17 family of interleukins consist of IL-17A, B, C, D, E, and F. In psoriasis, IL-17A is known as the principal effector molecule that triggers inflammation, with the closely related IL-17F playing a similarly significant role." (PMID 31130981, 2019). "Treatment with secukinumab, an IL-17A blocker for treating psoriasis and ankylosing spondylitis, preceded one case of pemphigus and another case of severe, ulcerative lichenoid mucositis." (PMID 31308976, 2019). "A fully human monoclonal antibody that selectively neutralizes IL-17A, a key cornerstone cytokine involved in the development of psoriasis, is an approved treatment for patients with moderate to severe plaque psoriasis." (PMID 32010143, 2019). "Medications targeting IL-17A showed efficacy in psoriasis and arthritis, which implies that translating these in vitro findings into future clinical use is feasible." (PMID 31083515, 2019).
psoriasis (continued). "This novel IL-19 biomarker assay allowed us to demonstrate for the first time that decreases in serum IL-19 levels precede clinical responses in psoriasis when the therapeutic anti-IL-17A antibody ixekizumab is administered." (PMID 30914699, 2019). "The other cytokines analyzed in the plasma of K14-IL-17Aind/+ mice had no relevant increase compared to control mice, stressing the mainly IL-17A-driven myeloid activation cascade in psoriasis." (PMID 31480330, 2019). "IL-1β and IL-23 are induced during IMQ-induced psoriasis and trigger the expression of Il17a from γδ T cells." (PMID 31622280, 2019). "A T cell-mediated production of IL-17A has also been shown for human psoriasis.To mimic this situation and to study downstream events, mice overexpressing IL-17A only in keratinocytes have been generated." (PMID 32010143, 2019). "Noticeably, the increased levels of IL-36α, IL-36β and IL-36γ in lesional skin were in good correlation with central cytokines of psoriasis pathology: IL-22, IL-17A, TNF-α and IFN-γ." (PMID 30634937, 2019). "Our results demonstrate an importance of IκBζ not only in IMQ- and IL-36–triggered psoriasis but also in K14-IL17Aind mice, which overexpress IL-17A specifically in keratinocytes." (PMID 31622280, 2019). "Correlation (R-values) of IL17A, IL22, and IL23A with genes linked to psoriasis susceptibility through genome-wide association studies." (PMID 31019502, 2019). "We have shown before that dermal over-expression of the cytokine IL-17A (K14-IL-17Aind/+) in mice results in severe psoriasis-like skin disease and simultaneous endothelial dysfunction, vascular inflammation, and arterial hypertension." (PMID 31480330, 2019). "The IL-17A-targeting biological Secukinumab which is approved in the treatment of psoriasis is already under investigation in AD (NCT02594098 and NCT03568136)." (PMID 31371767, 2019). "In psoriasis, IL-17A stimulated inflammation leads to acanthosis and plaque formation, which is reduced via it’s inhibition." (PMID 31488067, 2019). "Interleukin (IL)-17A is involved in mucocutaneous defense and plays a critical role in the pathogenesis of a range of immune-mediated diseases, including psoriasis (PsO), psoriatic arthritis (PsA), and ankylosing spondylitis (AS)." (PMID 31046809, 2019). "The central role of IL-17A in the pathophysiology of psoriasis has recently been reviewed elsewhere and will only be briefly described here." (PMID 30127781, 2018). "Secukinumab is a monoclonal antibody directed against IL-17A, registered for the treatment of psoriasis, psoriatic arthritis, and ankylosing spondylitis." (PMID 30304837, 2018). "Recent findings provide new evidence that is slightly but definitely changing the paradigmatic view of the pathogenesis of psoriasis: from Th17- to IL-17A-driven disease." (PMID 30127781, 2018). "Our lab showed that serum from hyperlipidemic mice enhances IL-6 production by DCs, driving IL-17A production by autoreactive CD1b-restricted T cells in a model of psoriasis." (PMID 30061888, 2018). "Flow cytometry analysis revealed a shared increase in the percentage of CD4+ T regulatory cells in all psoriasis subtypes relative to controls, whereas distinct psoriasis subtypes displayed differences in IL-17A, IFN-gamma, and IL-22 production." (PMID 30054515, 2018). "This will lead to an in-depth discussion of the IL-17 family of cytokines and the contribution of IL-17 isoforms other than IL-17A to psoriasis manifestations in the skin and its comorbidities." (PMID 30127781, 2018). "The immunological events leading to the described epidermal changes are well understood and various “biologics” against different inflammatory cytokines such as TNF-α, IL-17A, or IL-12/IL-23 show promising results in the therapy of psoriasis." (PMID 30555471, 2018). "Two approved antibody based therapeutics targeting IL-17A, Secukinumab and Ixekizumab, are currently being used for treatment of moderate to severe psoriasis." (PMID 29329326, 2018).
psoriasis (continued). "Psoriasis is driven by T cell activation associated with the secretion of proinflammatory cytokines, including tumor necrosis factor-α (TNF-α), interleukin (IL)-17A, IL-22, and interferon IFN-γ." (PMID 30109481, 2018). "More recently, bimekizumab, a monoclonal antibody targeting IL-17A and IL-17F, demonstrated high efficacy in psoriasis." (PMID 30109481, 2018). "Our study added novel findings that topical MaR1 inhibits IMQ-induced psoriasis in an animal model through inhibition of IL-17A production by both γδTCRmid+ and CD4+ cells in the skin." (PMID 29615641, 2018). "Many cytokines are involved in psoriasis development; however, data identify IL-17A as the major effector cytokine driving pathogenesis." (PMID 30109481, 2018). "IL-17A was initially thought to be a “unique” cytokine, exclusively produced by T cells in psoriasis." (PMID 30127781, 2018). "For instance, IL-17A acts on keratinocytes to induce the expression of several chemokines leading to the recruitment of immune cells that characterized psoriasis." (PMID 30693283, 2018). "It was long thought that neutrophils were an abundant source of IL-17A in psoriasis; however, emerging data indicate that highly purified human neutrophils are not capable of expressing IL-17A or other IL-17 family cytokines in vitro." (PMID 30109481, 2018). "The direct blockade of IL-17A by Secukinumab (Cosentyx®) and Ixekizumab (Taltz®) also leads to a convincing improvement in psoriasis." (PMID 29963046, 2018). "Accordingly, biologics that target IL-17A function lead to rapid and dramatic improvement of skin and joint symptoms in psoriasis and PsA." (PMID 30109481, 2018). "Today, the belief that Th17 cells mediate psoriasis is moving to the concept of psoriasis as an IL-17A-driven disease." (PMID 30127781, 2018). "Th17 cells and their downstream effector molecules, which include IL-17A, IL-22, and TNF-α, have been shown to induce keratinocyte proliferation and other hallmark features of psoriasis." (PMID 29619073, 2018). "In the IL-23/Th17 axis model of psoriasis, IL-23 is able to produce and induce Th17 cell lymphocyte activation, which subsequently releases IL-17A, IL-17C, IL-17F, IL-22 and other related pro-inflammatory cytokines." (PMID 30544700, 2018). "Consistent with this, Pla2g2f deficiency in keratinocytes markedly impairs the induction of several psoriasis markers in response to IL-17A or IL-22." (PMID 30546811, 2018). "In summary, the observations made to date suggest that circulating CLA+ T cells in psoriasis patients produce increased amounts of IL-17A, IL-17F, and IL-9, in comparison to healthy controls, when activated by S. pyogenes." (PMID 30013558, 2018). "Secukinumab is a fully human anti-IL-17A immunoglobulin G 1κ (IgG1κ) monoclonal antibody that selectively binds to and neutralizes IL-17A to alleviate diseases such as psoriasis, psoriatic arthritis and ankylosing spondylitis." (PMID 29892286, 2018). "The influence of salt diet on the response to IL-23p40 or IL-17A blocking agents (ustekinumab and secukinumab/ixekizumab, respectively) in patients with psoriasis, CD or spondyloarthritis is another relevant question to examine." (PMID 29740348, 2018). "Recapitulating psoriasis skin, IL-17A+TNF-α treatment lead to increased expression of DEFB4, PI3, LCN2, S100A7, and IL36G mRNA over a 72 h time course without marked deterioration of tissue structure." (PMID 30321197, 2018). "In the background of psoriasis, secukinumab only reduces the autoimmune inflammation resulting from IL-17A while leaves other immune functions undisturbed." (PMID 29892286, 2018). "Th17 cells and its effective cytokine IL-17A play an important role in the pathogenesis of abnormal immune responses in psoriasis." (PMID 29523162, 2018).